HINFP (histone H4 transcription factor)
Description:
Transcriptional repressor that binds to the consensus sequence 5'-CGGACGTT-3' and to the RB1 promoter. Transcriptional activator that promotes histone H4 gene transcription at the G1/S phase transition in conjunction with NPAT. Also activates transcription of the ATM and PRKDC genes. Autoregulates its expression by associating with its own promoter.
Synonyms: HiNF-P; MIZF; ZNF743; DKFZP434F162
Tractability: PROTAC: UniProt records ubiquitination sites on it; ubiquitination databases record sites on it.
Gene: Protein-coding gene on chromosome 11 (119,121,509 to 119,136,059, forward strand). Ensembl gene ENSG00000172273.
Subcellular location: Nucleus
Gene Ontology:
Molecular function: DNA binding; DNA-binding transcription activator activity, RNA polymerase II-specific; DNA-binding transcription factor activity; enzyme binding; histone binding; protein binding; RNA polymerase II transcription regulatory region sequence-specific DNA binding; transcription cis-regulatory region binding; DNA-binding transcription factor activity, RNA polymerase II-specific; RNA polymerase II cis-regulatory region sequence-specific DNA binding; chromatin binding; DNA-binding transcription repressor activity, RNA polymerase II-specific
Biological process: cell cycle G1/S phase transition; DNA damage checkpoint signaling; DNA repair; establishment of protein localization; G1/S transition of mitotic cell cycle; myoblast differentiation; negative regulation of DNA-templated transcription; negative regulation of gene expression; positive regulation of DNA-templated transcription; positive regulation of gene expression; positive regulation of transcription by RNA polymerase II; regulation of DNA-templated transcription; in utero embryonic development; regulation of transcription by RNA polymerase II; DNA-templated transcription; negative regulation of transcription by RNA polymerase II
Cellular component: Cajal body; nucleolus; nucleoplasm; nucleus
Genetic constraint (gnomAD): Loss-of-function variants: 19 observed, 55.37 expected, observed/expected ratio (o/e) 0.34, 90% interval 0.24 to 0.5. The upper end of that interval is the gene's LOEUF score, 0.5, which puts it in group 2 of 6, group 1 being the genes least tolerant of losing a copy. Missense variants: 505 observed, 699.54 expected, observed/expected ratio (o/e) 0.72, 90% interval 0.67 to 0.78. Synonymous variants: 247 observed, 257.94 expected, observed/expected ratio (o/e) 0.96, 90% interval 0.86 to 1.06.
Homologues: Orthologues: chimpanzee HINFP (98% identical), macaque HINFP (98% identical), dog HINFP (92% identical), pig HINFP (91% identical), rabbit HINFP (90% identical), rat Hinfp (88% identical), guinea pig HINFP (88% identical), mouse Hinfp (85% identical), tropical clawed frog hinfp (56% identical), zebrafish hinfp (55% identical), Caenorhabditis elegans hinf-1 (25% identical), Drosophila melanogaster zfh1 (21% identical), and 2 more.
Diseases named in the same sentence as HINFP in open-access papers:
HINFP is named in the same sentence as 13 diseases in open-access papers, as found by Europe PMC text mining. Sharing a sentence is not in itself a finding about the gene and the disease. The quoted sentences say what the papers report.
lung carcinoma (2 papers, 2021 to 2025). "Previous studies have demonstrated that these transcription factors play critical roles in various cancers; for example, HINFP shows significant regulatory effects in bladder cancer, POU2F2 is linked to lung cancer, and JUND and FOXC1 are key in colorectal and breast cancer, respectively." (PMID 40417238, 2025).
cancer (2 papers, 2019 to 2025). A tumor composed of atypical neoplastic, often pleomorphic cells that invade other tissues.
tumor (2 papers, 2017 to 2020). "In the first pathway, in early-stage CRC, the upregulated CASC2 transmits the signal to HINFP, which is modified by ubiquitination to inhibit tumor growth, and transmits the signal to TF TCF3 through SMG8." (PMID 32211020, 2020). "To determine why normal and tumor cells respond differentially to CASP8AP2 loss, we examined the expression profiles of non-histone genes after CASP8AP2, NPAT and HINFP siRNA treatment." (PMID 27929715, 2017).
metabolism disorders (1 paper, 2021). "Based on the pseudo-temporal continuum profile, we identified the TF (ALX4, HINFP, CEBPA, CEBPB, DMBX1, MLXIPL, ONECUT1, and RBPJL) and depicted the regulated kernel genes co-networks, which were subjected to the metabolism disorders." (PMID 33462196, 2021).
neurodevelopmental disorder (1 paper, 2020). A behavioral and cognitive disorder with onset during the developmental period that involves impaired or aberrant development of intellectual, motor, or social functions. "The roles of the TFAP2A and HINFP have not yet been described in other neurodevelopmental disorders." (PMID 33080834, 2020).
HINFP also shares sentences with these, for which no sentence is quoted: Alzheimer disease (1 paper); bladder cancer (1); breast carcinoma (1); colon cancer (1); COVID-19 (1); microcephaly (1); microphthalmia (1); neurological diseases (1).